EXOSC4 (exosome component 4)
Description:
Non-catalytic component of the RNA exosome complex which has 3'->5' exoribonuclease activity and participates in a multitude of cellular RNA processing and degradation events. In the nucleus, the RNA exosome complex is involved in proper maturation of stable RNA species such as rRNA, snRNA and snoRNA, in the elimination of RNA processing by-products and non-coding 'pervasive' transcripts, such as antisense RNA species and promoter-upstream transcripts (PROMPTs), and of mRNAs with processing defects, thereby limiting or excluding their export to the cytoplasm. The RNA exosome may be involved in Ig class switch recombination (CSR) and/or Ig variable region somatic hypermutation (SHM) by targeting AICDA deamination activity to transcribed dsDNA substrates. In the cytoplasm, the RNA exosome complex is involved in general mRNA turnover and specifically degrades inherently unstable mRNAs containing AU-rich elements (AREs) within their 3' untranslated regions, and in RNA surveillance pathways, preventing translation of aberrant mRNAs. It seems to be involved in degradation of histone mRNA. The catalytic inactive RNA exosome core complex of 9 subunits (Exo-9) is proposed to play a pivotal role in the binding and presentation of RNA for ribonucleolysis, and to serve as a scaffold for the association with catalytic subunits and accessory proteins or complexes. EXOSC4 binds to ARE-containing RNAs.
Synonyms: RRP41; SKI6; hRrp41p; FLJ20591; Rrp41p; RRP41A; Ski6p; p12A
Tractability: Small molecule: a structure with a bound ligand is known; it has a binding pocket of medium quality. PROTAC: ubiquitination databases record sites on it; its protein half-life has been measured.
Gene: Protein-coding gene on chromosome 8 (144,078,621 to 144,081,244, forward strand). Ensembl gene ENSG00000178896.
Subcellular location: Cytoplasm; Nucleus, nucleolus; Nucleus; Nucleus, nucleoplasm
Subcellular location (Human Protein Atlas): Cytosol; Nucleoplasm; Vesicles
Pathways (Reactome):
Metabolism of RNA: Butyrate Response Factor 1 (BRF1) binds and destabilizes mRNA; KSRP (KHSRP) binds and destabilizes mRNA; Major pathway of rRNA processing in the nucleolus and cytosol; Nuclear RNA decay; Tristetraprolin (TTP, ZFP36) binds and destabilizes mRNA; mRNA decay by 3' to 5' exoribonuclease
Cellular responses to stimuli: ATF4 activates genes in response to endoplasmic reticulum stress
Gene Ontology:
Molecular function: mRNA 3'-UTR AU-rich region binding; protein binding; RNA exonuclease activity; 3'-5'-RNA exonuclease activity; RNA binding
Biological process: defense response to virus; DNA deamination; histone mRNA catabolic process; maturation of 5.8S rRNA; nuclear mRNA surveillance; nuclear-transcribed mRNA catabolic process; positive regulation of cell growth; RNA catabolic process; RNA processing; poly(A)-dependent snoRNA 3'-end processing; rRNA catabolic process; rRNA processing; U4 snRNA 3'-end processing
Cellular component: cytoplasm; cytosol; euchromatin; exosome (RNase complex); nucleolus; nucleoplasm; nucleus; cytoplasmic exosome (RNase complex); nuclear exosome (RNase complex); nucleolar exosome (RNase complex); exoribonuclease complex
Genetic constraint (gnomAD): Loss-of-function variants: 17 observed, 18.75 expected, observed/expected ratio (o/e) 0.91, 90% interval 0.62 to 1.36. The upper end of that interval is the gene's LOEUF score, 1.36, which puts it in group 5 of 6, group 1 being the genes least tolerant of losing a copy. Missense variants: 337 observed, 311.94 expected, observed/expected ratio (o/e) 1.08, 90% interval 0.99 to 1.18. Synonymous variants: 148 observed, 137.59 expected, observed/expected ratio (o/e) 1.08, 90% interval 0.94 to 1.23.
Homologues: Orthologues: chimpanzee EXOSC4 (100% identical), macaque EXOSC4 (100% identical), guinea pig EXOSC4 (99% identical), dog EXOSC4 (98% identical), rat Exosc4 (98% identical), pig EXOSC4 (97% identical), rabbit EXOSC4 (97% identical), mouse Exosc4 (96% identical), tropical clawed frog exosc4 (81% identical), zebrafish exosc4 (74% identical), Drosophila melanogaster Ski6 (52% identical), Caenorhabditis elegans exos-4.1 (43% identical). Paralogues in human: EXOSC6 (27% identical), EXOSC5 (24% identical).
Diseases named in the same sentence as EXOSC4 in open-access papers:
EXOSC4 is named in the same sentence as 28 diseases in open-access papers, as found by Europe PMC text mining. Sharing a sentence is not in itself a finding about the gene and the disease. The quoted sentences say what the papers report.
colorectal cancer (3 papers, 2021 to 2022). A primary or metastatic malignant neoplasm that affects the colon or rectum. "EXOSC4 functioned as a potential oncogene in the development and progression of colorectal cancer and was identified as a potential diagnostic molecular biomarker." (PMID 35004283, 2021). "Cell proliferation assays revealed that knockdown of EXOSC4 by siRNA caused a marked reduction in the growth of the pancreatic cancer cell lines MIA Paca-2, AsPC-1, Hs766T, and SW1990 as well as the colorectal cancer cell line HCT116 cells." (PMID 35008922, 2022). "An array-CGH analysis revealed gain of chromosome 8q in colorectal cancer, and microarray analysis revealed that EXOSC4 was overexpressed in colorectal cancer." (PMID 35008922, 2022). "In this study, we also showed that the EXOSC4 gene was amplified in colorectal cancer, although at a rate of less than 5%." (PMID 35008922, 2022). "Additionally, the enhancing expression of EXOSC2 directly regulated by tRNAGluUUC is closely related to breast cancer metastasis, while EXOSC3 and EXOSC4 can trigger the development of colonic and colorectal cancer, respectively." (PMID 36293016, 2022). "A recent report revealed that EXOSC4 interacts with and is regulated by STX2 and promotes the proliferation of colorectal cancer cells." (PMID 35008922, 2022). "Similarly, previous studies also identified the roles of EXOSC4 and EXOSC5 in predicting the prognosis of colorectal cancer and renal cell carcinoma, respectively." (PMID 36293016, 2022).
breast carcinoma (2 papers, 2022). "Among these 12 CanCord34 genes, the knockdown of PUF60, EXOSC4, or BOP1 was accompanied by the loss of cell viability in breast cancer cell lines." (PMID 36497066, 2022). "In addition, EXOSC4 overexpression leads to the increase of viability, foci formation, invasiveness, and migration of normal and cancer colon cells and its depletion decreases the proliferation of breast cancer cells." (PMID 35008922, 2022). "A recent study reported that EXOSC4 knockdown resulted in the downregulation of other RNA exosome components, EXOSC3 and EXOSC9, at the protein level in MDA-MB-231 cells, a breast cancer cell line." (PMID 35008922, 2022). "The results indicated that 17 of the CanCord34 genes’ transcripts, proteins, or both could be detected in the secretomes and plasma vesicles, including the EXOSC4 and PUF60 proteins, in the breast cancer secretome datasets." (PMID 36497066, 2022).
colon cancer (2 papers, 2022). "Further studies showed that EXOSC4 overexpression increased the tumorigenicity of colon cancer cells by promoting cell proliferation and cell invasion." (PMID 35008922, 2022). "EXOSC4 overexpression is also considered as a growth-promoting gene event in ovarian cancer, as it stimulates WNT signaling, and it enhances the invasion and tumor-forming potential of colon cancer cells." (PMID 36497066, 2022).
liver cancer (2 papers, 2018 to 2022). An epithelial or non-epithelial malignant neoplasm that arises from the liver. "EXOSC4 overexpression in liver cancer cells has been attributed to the hypomethylation of its promoter, and EXOSC4 downregulation inhibits the growth and invasiveness of liver cancer cells." (PMID 36497066, 2022). "Similarly, in patients with liver cancer, the EXOSC4 gene was found to be highly expressed, and its knock-down commonly inhibited cancer cell growth and invasion." (PMID 30340642, 2018).
pancreatic cancer (2 papers, 2022 to 2024). "A significant association was found between the alteration of EXOSC4 and overall and progression-free survival of pancreatic cancer patients." (PMID 35008922, 2022). "We further found that EXOSC4 alteration is associated with a poor prognosis of pancreatic cancer patients." (PMID 35008922, 2022). "We also found that EXOSC4 alteration was associated with poor disease prognosis in pancreatic cancer." (PMID 35008922, 2022). "Although EXOSC4 gene amplification was confirmed across multiple tumors, EXOSC4 gene amplification was associated with poor disease prognosis only in pancreatic cancer patients." (PMID 35008922, 2022). "Consistent with their results, we also showed that EXOSC4 knockdown led to the reduction in the viability of pancreatic and colorectal tumor cells, even though EXOSC4 alteration is associated only with a poor prognosis of pancreatic cancer patients." (PMID 35008922, 2022). "We found that the EXOSC4 gene is amplified in multiple cancer types and its amplification was associated with poor disease prognosis in pancreatic cancer patients." (PMID 35008922, 2022). "In conclusion, we demonstrated that the EXOSC4 gene is amplified across multiple cancer types and its amplification is associated with poor clinical outcomes in pancreatic cancer." (PMID 35008922, 2022). "We then focused on EXOSC4 in pancreatic cancer and investigated its role in pancreatic cancer cell viability and found that EXOSC4 knockdown led to the reduction in the growth and increase in the apoptotic cell death of pancreatic cancer cells." (PMID 35008922, 2022). "Future studies are needed to address the molecular mechanisms of target mRNA degradation by EXOSC4 in promoting pancreatic cancer development and progression." (PMID 35008922, 2022). "Although EXOSC4 regulates the expression of BIK and SESN2 mRNA in pancreatic cancer cells, how EXOSC4 recognizes the mRNAs is still unclear." (PMID 35008922, 2022). "We showed that EXOSC4 regulates the stability of SESN2 mRNA in pancreatic cancer cells; however, we were unable to evaluate the effects of EXOSC4 on BIK mRNA because of their low expression levels." (PMID 35008922, 2022). "Taken together, these results suggested that EXOSC4 is amplified and/or upregulated in pancreatic cancer tissues." (PMID 35008922, 2022). "We next performed immunohistochemical staining for EXOSC4 on primary pancreatic cancer tissues and tumor-adjacent pancreatic tissues from pancreatic cancer patients." (PMID 35008922, 2022). "In addition, GO and GSEA analyses revealed that the genes regulated by EXOSC4 in pancreatic cancer cells were enriched for genes involved in lysosome and apoptosis." (PMID 35008922, 2022). "Moreover, we found that EXOSC4 knockdown leads to the reduction in the growth of pancreatic cancer cells." (PMID 35008922, 2022). "Since EXOSC4 is localized in the nucleus of pancreatic cancer cells, EXOSC4 may regulate BIK expression via not only mRNA stability but also transcriptional regulation." (PMID 35008922, 2022). "Altogether, our results suggested that EXOSC4 inhibition may be a novel therapeutic approach for pancreatic cancer treatment." (PMID 35008922, 2022). "We then validated the gene amplification of the EXOSC4 gene, but not that of genes encoding other RNA exosome components, in pancreatic cancer patients using data from Pancreatic Cancer [UT Southwestern (UTSW)] by the cBioPortal database." (PMID 35008922, 2022). "We speculate that EXOSC4 knockdown leads to the reduction in the growth of pancreatic tumor cells by upregulation of SESN2 and BIK mRNA." (PMID 35008922, 2022). "Moreover, we demonstrated that EXOSC4 is required for the survival of pancreatic cancer cells." (PMID 35008922, 2022). "We concluded that EXOSC4-mediated downregulation of BIK and SESN2 is required for the proliferation of pancreatic cancer cells." (PMID 35008922, 2022).
pancreatic cancer (continued). "Our study provides evidence for EXOSC4-mediated regulation of BIK and SESN2 mRNA in the survival of pancreatic tumor cells." (PMID 35008922, 2022). "Similarly, EXOSC4 has been shown to destabilize SESN2 mRNA, influencing the proliferation of pancreatic cancer cells." (PMID 38164180, 2024). "EXOSC4 may degrade SESN2 mRNA levels by regulating EXOSC10 and DIS3 family protein levels in pancreatic cancer cells." (PMID 35008922, 2022). "Furthermore, EXOSC4 knockdown increased mRNA levels of BIK and SESN2, which regulate apoptosis in pancreatic cancer cells." (PMID 35008922, 2022). "Furthermore, we revealed that EXOSC4 knockdown induces BIK and SESN2 mRNA levels in pancreatic cancer cells." (PMID 35008922, 2022). "We found that EXOSC4 expression was higher in pancreatic tumors than in noncancerous tissues." (PMID 35008922, 2022).
breast tumours (1 paper, 2015). "EXOSC4 which encodes the EXOSC4 subunit of the RNA exosome complex that is important for RNA processing and degradation, is upregulated in 24 % breast tumours, and confers poor survival (p = 0.012)." (PMID 26427375, 2015).
lung adenocarcinoma (1 paper, 2018). A carcinoma that arises from the lung and is characterized by the presence of malignant glandular epithelial cells. "In lung adenocarcinoma, EXOSC4 has been reported to be extremely highly expressed and closely associated with cancer cell proliferation and was, therefore, recognized as a new prognostic marker." (PMID 30340642, 2018).
meningioma (1 paper, 2021). A generally slow growing tumor attached to the dura mater. "The expression of EPN1, EXOSC4, H2AX, and MZT2B was related to both WHO grades and age of patients and was significantly different between normal meningeal tissues and meningiomas." (PMID 35004283, 2021). "Among 32 key hub genes screened, EPN1, EXOSC4, H2AX, and MZT2B not only showed significant differences between meningioma molecular subtypes but also had the potential to be the marker genes of specific meningioma subtype." (PMID 35004283, 2021). "EPN1, EXOSC4, H2AX, and MZT2B not only showed significant differences between meningioma molecular subtypes but also had the potential to be the marker genes of specific meningioma subtypes." (PMID 35004283, 2021).
microcephaly (1 paper, 2025). A congenital or acquired developmental disorder in which the circumference of the head is smaller than normal for the person's age and sex. "This variant was identified in 2 patients with microcephaly, but the symptoms could not be specifically attributed to the EXOSC4 variant because the patients also had a pathogenic variant in another protein, PAXBP1, that appears to explain the disease." (PMID 39982806, 2025).
Sepsis (1 paper, 2020). Sepsis is defined as life-threatening organ dysfunction caused by a dysregulated host response to infection. "In adult sepsis there is indirect interaction between GPR84, CD177, and TDRD9 through EXOSC4 and with CD177 through NECAB1." (PMID 32318053, 2020). "In adult sepsis, genes TDRD9, GPR84, and CD177 interacted via overlapped genes EXOSC4 (TDRD9 ↔ GPR84 ↔ CD177), ZDHHC19 (TDRD9 ↔ CD177) and NECAB1 (GPR84 ↔ CD177)." (PMID 32318053, 2020).
viral infections (1 paper, 2020). "Herein, the candidate genes PARP10, EXOSC4, GFUS and EEF1D, involved in various viral infections, were identified." (PMID 33255903, 2020).
cancer (5 papers, 2015 to 2022). A tumor composed of atypical neoplastic, often pleomorphic cells that invade other tissues. "We discovered that the EXOSC4 gene, which encodes a barrel component of the RNA exosome, was amplified across multiple cancer types." (PMID 35008922, 2022). "To investigate the correlation of EXOSC4 alteration with the outcome of cancer patients, we next examined overall and progression-free survival by Kaplan–Meier analysis using the cBioPortal database." (PMID 35008922, 2022). "Meanwhile, we found that MYC and POU5F1B were co-amplified with EXOSC4 at a high frequency but co-expressed with low correlation in all nine cancer types." (PMID 35008922, 2022). "We found that the gene encoding exosome component 4 (EXOSC4), an EXO9 component, was amplified in multiple cancer types using the data from The Cancer Genome Atlas (TCGA) PanCancer Atlas." (PMID 35008922, 2022). "In addition, we found that EXOSC4 knockdown caused the upregulation in mRNAs’ levels of BIK and SESN2, both of which induce apoptosis in cancer cells." (PMID 35008922, 2022). "We found that HSF1 was co-amplified and co-expressed with EXOSC4 in all nine cancer types." (PMID 35008922, 2022). "For example, the present study provided new insights into the involvement of several members of the CanCord34 genes (i.e., EXOSC4, PUF60, and BOP1) in cell viability, cancer stem cell biology, and extracellular communications via secreted plasma vesicles." (PMID 36497066, 2022). "Next, we examined the co-amplification and co-expression of EXOSC4 with HSF1, MYC, and POU5F1B, which are located on chromosomes 8q24.3, 8q24.21, and 8q24.21, respectively, in nine different cancer types." (PMID 35008922, 2022). "To validate our findings, we conducted a study of the literature by randomly selecting five genes (DBF4, MCM2, ID3, EXOSC4, and CDKN3) from the 565 potential cancer genes." (PMID 25866773, 2015). "Similarly, EXOSC4 (exosome component 4), a component of the RNA exosome complex, regulates growth, WNT signaling, and surface transport in cancer cells." (PMID 36497066, 2022).
tumor (4 papers, 2019 to 2025). "This enabled us to identify the core genes associated with tumor stemness induced by tumor intrinsic variations and finally we selected four genes: RAD21, EXOSC4, CSE1L and RAE1." (PMID 40406120, 2025). "EXOSC4 expression was identified in the cytoplasm and nucleus of tumor cells, while few cells showed EXOSC4 expression in tumor-adjacent pancreatic tissues." (PMID 35008922, 2022).
infection (2 papers, 2017 to 2018). The state of being infected such as from the introduction of a foreign agent such as serum, vaccine, antigenic substance or organism. "Here, we found that EXOSC4 was commonly targeted by the meningitic and the non-meningitic E. coli strains, indicating that this cellular protein is a non-specific infection-related protein." (PMID 30340642, 2018).
neurodevelopmental disorder (2 papers, 2024 to 2025). A behavioral and cognitive disorder with onset during the developmental period that involves impaired or aberrant development of intellectual, motor, or social functions. "An EXOSC4 variant has recently been added to the list of RNA exosome subunits linked to inborn neurodevelopmental disorders." (PMID 39982806, 2025). "In summary, the work presented here expands the group of disorders termed RNA exosomopathies by reporting a neurodevelopmental disorder in two sisters homozygous for a pathogenic missense variant in the EXOSC4 gene." (PMID 39009343, 2024). "Here, we report the identification of a novel, homozygous missense variant, p.L187P, in the RNA exosome gene EXOSC4 that is linked to a neurodevelopmental disorder in two siblings." (PMID 39009343, 2024). "EXOSC4 has been linked to a neurodevelopmental disorder with some mild brain atrophy reported." (PMID 39982806, 2025).
EXOSC4 also shares sentences with these, for which no sentence is quoted: Breast invasive carcinoma (1 paper); colorectal tumor (1); Esophageal carcinoma (1); head and neck squamous cell carcinoma (1); melanoma (1); Obesity (1); ovarian carcinoma (1); ovarian serous cystadenocarcinoma (1); pancreatic adenocarcinoma (1); prostate adenocarcinoma (1); renal cell carcinoma (1); Stomach adenocarcinoma (1); uterine carcinosarcoma (1).